AURKA (aurora kinase A)
Diseases named in the same sentence as AURKA in open-access papers (continued):
Sharing a sentence is not in itself a finding about the gene and the disease.
tumor (continued). "Analysis of the TCGA dataset revealed that AURKA was abnormally expressed in 24 tumors and involved in tumor progression." (PMID 35875069, 2022). "Several mitosis-associated genes, including AURKA, DLGAP5, TPX2, KIF11, and CKAP5, were overexpressed in tumor tissues, and associated with cell proliferation and poor OS." (PMID 36499051, 2022). "Altogether, AURKA exerts a tumour-promoting function by preventing SIN1 from being degraded by the ubiquitin–proteasome system." (PMID 36471438, 2022). "We explored the potential role of AURKA in NPC evolution by analyzing tumor tissues and normal tissues in the GSE12452 and GSE13597 datasets." (PMID 36072667, 2022). "The overexpression of many other amplified genes (e.g., AURKA, HRH3, MIR646, MRGBP, PCK1, PMEPA1, SLCO4A1-AS1, SOX18, TNFRSF6B) is associated with PDAC cell proliferation and tumour growth." (PMID 36289850, 2022). "Not surprisingly, the combination of AURKA kinase inhibitor (VX680) and AURKA nuclear localization inhibitors (JNJ or PHA) produces an additive tumor growth-suppressing effect." (PMID 35361747, 2022). "Using single cell sequencing, we identified the CNV of chromosome 20q in LN metastasis compared to the primary tumor and found that amplification of AURKA (protein: Aurora Kinase A (Aurora A)) and BCL2L1 (protein: Bcl-xL) was associated with LN metastasis." (PMID 36077449, 2022). "Tissues from FLO-1 and OE33 tumor xenograft mouse models were investigated to examine the regulation of IRE1α by AURKA in vivo." (PMID 35326553, 2022). "To investigate the link between AURKA and immune cell infiltration, we calculated the proportion of these 21 cells infiltrating the tumor microenvironment using the CIBERSORT algorithm." (PMID 36072667, 2022). "FBXL7 gene functions are poorly understood, but the gene’s role as a tumor suppressor has been proposed based on its target proteins, AURKA, BIRC5 and c-SRC." (PMID 35887149, 2022). "Compared with those of control group tumours, knocking down AURKA markedly decreased tumour volumes and weights." (PMID 36471438, 2022). "Both AURKA and AURKB are highly expressed in HCC, and overexpression is associated with tumor aggressiveness, an unfavorable prognosis, and poorer outcomes." (PMID 35062934, 2022). "These phenomena suggested the tumor-suppressive functions of miR-363-3p in CRC were partly dependent on its regulatory function on AURKA." (PMID 35166647, 2022). "Promotes STAT3 phosphorylation and binds AURKA, leading to Aurora A expression in drug‐resistant tumor cells, thereby promoting the expression of drug resistance." (PMID 37786890, 2022). "Regulation of the cell cycle has implications in anti-tumor immunity contributed by AURKA, a member in the immune-oncogenic gene signature." (PMID 35205315, 2022). "We found aberrant overexpression of AURKA in PTC, which was highly associated with a poor prognosis and advanced tumour stage, suggesting prognostic value for AURKA." (PMID 36471438, 2022). "AURKA, as an oncogene, is involved in tumor occurrence through various mechanisms, thus providing a potential target for tumor therapy." (PMID 35217647, 2022). "It is believed that this work would aid in related research while providing additional biological information about the mechanism of AURKA in tumor immunity and the tumor microenvironment in future research." (PMID 36685952, 2022).
tumor (continued). "Upon the discovery of several synthetic lethal interactions of AURKA and tumor suppressors, additional clinical studies of AURKA inhibitors that are tailored to the specific tumor suppressor status should be performed in the future." (PMID 34050264, 2021). "Prior results in other tumor entities pointed towards a role of Aurora kinase A in regulating glycolysis and oxidative energy metabolism, but our results are unique due to the identified signaling pathway and its potential translational implications." (PMID 34471141, 2021). "The synthetic lethality of ARID1A and AURKA has been further demonstrated in ARID1A-deficient ovarian clear cell carcinoma (OCCC) cells and in mouse tumor xenograft models of CRC83." (PMID 34050264, 2021). "AURKA-induced CIN represents one of its most established oncogenic functions because the emergence of CIN confers tumor heterogeneity, drug resistance, and poor outcome." (PMID 33674749, 2021). "The present study focuses on one such feedback loop, which was discovered between AURKA and a tumor-suppressor NKX3.1 in CRPC and NEPC cells." (PMID 34625072, 2021). "Our analyses identified drugs targeting CDK4, CDK6 and AURKA as strong candidates for MB; all of these genes are well validated as drug targets in other tumour types." (PMID 34154646, 2021). "Phosphorylation of LDHB by AURKA at Ser162 amplifies its activity in reducing pyruvate to lactate, thus promoting glycolysis and biosynthesis and promoting tumor growth." (PMID 33451333, 2021). "Because TGF-β and AURKA signaling pathways provide attractive druggable targets to halt tumor progression, we developed tumor xenografts to define in vivo the efficacy of dual TGF-β/AURKA targeted therapy in combination with DTX." (PMID 33674749, 2021). "Significantly, the combination of docetaxel (DTX) with dual TGF-β and AURKA pharmacologic targeting impaired tumor relapse and the emergence of distant metastasis." (PMID 33674749, 2021). "The expression of AURKA in DLBCL tumor tissues from DLBCL patients and normal lymphoid tissues from healthy volunteers was detected using qRT-PCR and IHC assays." (PMID 34565287, 2021). "The results showed that as tumor purity increasing, AURKA and FAM83A expression levels are positive related (r=0.333, P=2.99e-14)." (PMID 33613763, 2021). "Merlin suppresses tumor development through distinct mechanisms and is a substrate of AURKA that is phosphorylated at its main regulatory site, Ser518, during mitosis." (PMID 33451333, 2021). "If the AURKA activity in tumor cells was disrupted, the accumulation of cells in G2/M phase and delayed mitotic entry were observed." (PMID 32978717, 2021). "Recent work has highlighted aurora kinase A (AURKA) as a synthetic lethal partner of multiple tumor suppressors." (PMID 34050264, 2021). "AURKA-mediated phosphorylation can regulate the functions of AURKA substrates, some of which are mitosis regulators, tumor suppressors or oncogenes." (PMID 33451333, 2021). "The role of AURKA overexpression in tumor progression has been reported in a variety of human malignancies." (PMID 34332577, 2021). "Given the protein-protein interaction, functional and survival analyses, we propose CCNB2and AURKA hub modules as potential drivers of proliferation and metastasis in breast cancercells." (PMID 34455715, 2021). "These regulators are usually tumor suppressors, and inhibition of AURKA is one of the mechanisms explaining their tumor-suppressive functions." (PMID 33451333, 2021). "AURKA can phosphorylate RAS association domain family 1 isoform A (RASSF1A) protein, which is a novel tumor suppressor." (PMID 34066975, 2021). "We found that AURKA inhibition as a single agent in a mouse xenograft model of RCC had a modest effect on reducing tumor burden when tumors were already palpable, but was competent in preventing tumors from taking when treated at an earlier time point." (PMID 34002003, 2021).
tumor (continued). "Aurora kinase A (AURKA) is another possible candidate as a common synthetic lethal partner of different tumor suppressors that have recently been identified by our group and other research groups." (PMID 34050264, 2021). "We made the unexpected and important finding that the response to Aurora kinase A inhibitors depends on glycolysis and that tumor cells with an oxidative metabolic phenotype will be more resistant to Aurora kinase A inhibitor treatment." (PMID 34471141, 2021). "The combination of docetaxel (DTX) with dual TGF-β (galunisertib) and AURKA (alisertib) pharmacologic targeting impaired tumor relapse and the emergence of distant metastasis." (PMID 33674749, 2021). "In HCC, the overexpression of AURKA has been reported to be related to aggressive tumor characteristics, chemotherapy resistance, and poor prognosis." (PMID 35059393, 2021). "Activation of positive regulators of AURKA or elimination of negative regulators of AURKA is also involved in AURKA-mediated tumor development." (PMID 34050264, 2021). "Next, we systematically explored the relationship between the expression of 37 common DEGs in tumor tissues and OS rate in TCGA and constructed a novel prognosis-related model composed of five genes (AURKA, PZP, RACGAP1, ACOT12 and LCAT)." (PMID 34336648, 2021). "The Gene Expression Profiling Interactive Analysis 2 was applied to analyze AURKA expression in DLBC tumor tissues and normal lymphoid tissues." (PMID 34565287, 2021). "The inhibition of aurora kinase A (AURKA), one of the four switch genes identified, inhibited tumor growth via apoptosis similarly in all tumor subtypes in in vitro and in vivo experiments." (PMID 34638242, 2021). "Given that AURKA is expressed and activated only during mitosis, AURKA inhibitors likely target tumor cells relatively specifically with less damage to normal cells." (PMID 34868993, 2021). "For other genes, AURKA, PTTG1, CDC20, SLC7A5, E2F8, TPX2, and TUBA4A, high expression in the high-risk group was linked to tumour growth and metastasis." (PMID 34131308, 2021). "Nonetheless, given that treatment of RCC cell lines, with elevated AURKA expression, using NVP-BEZ235 showed decreased AURKA expression, we wanted to correlate this decrease in AURKA expression to reduced tumor burden in an in vivo model of RCC." (PMID 34002003, 2021). "The five studies discussed herein reveal two common mechanisms by which AURKA contributes to synthetic lethality with tumor suppressors." (PMID 34050264, 2021). "We assessed the ability of such compounds to disrupt the interaction between AURKA and N-Myc in vitro, using Surface Plasmon Resonance competition assays, and in tumor cell lines overexpressing MYCN, by performing Proximity Ligation Assays." (PMID 34884931, 2021). "Mechanistically, SOCS2-AS1 exerts its tumor-suppressive activity via promotion of Aurora kinase A (AURKA) degradation." (PMID 33824269, 2021). "Correspondingly, AURKA inhibitor PHA-739358 (danusertib) was confirmed to be effective on the growth of NE tumor cells and mouse xenograft models." (PMID 34956090, 2021). "AURKA has been identified as a synthetic lethal target for several tumor suppressors, including ARIDIA, SNF, and SMARCA4, as well as RB1." (PMID 34359608, 2021). "AURKA overexpression leads to consequent activation of the NF-κB signaling pathway via negative regulation of IκBα and induces tumor invasion." (PMID 32469983, 2020). "In this study, we evaluated the expression of AURKA in 18 types of tumor tissues and matched normal tissues." (PMID 32851091, 2020). "Four out of five datasets showed that AURKA mRNA was significantly highly expressed in tumor tissues." (PMID 33117697, 2020).
tumor (continued). "In the mouse model, the upregulation of AURKA was positively correlated with the size of the transplanted tumor in the presence of MLN8237 treatment." (PMID 31920463, 2020). "In the TCGA dataset, AURKA was significantly more expressed in tumour tissue in comparison with normal oesophageal epithelium." (PMID 32429269, 2020). "MLN8237 (Alisertib) and its predecessor, MLN8054, are AURKA specific small molecule inhibitors and displayed antiproliferative activity in numerous human tumor cell lines, including lung and prostate." (PMID 33167327, 2020). "For instance, Liu and colleagues found increased expression of AURKA in NSCLC tumor samples that correlated with decreased time to progression and overall survival." (PMID 33202573, 2020). "Recent studies showed that the combination of a bromodomain inhibitor with a CDK7 inhibitor, an AURKA inhibitor or an HDAC inhibitor is significantly more effective in suppressing MYCN-driven NB tumor growth than either drug alone." (PMID 33628735, 2020). "AURKA knockdown contributes to the eradication of senescent tumor cells induced by AURKA inhibitors." (PMID 31920463, 2020). "The abnormal expression of AURKA in various solid tumors is closely related to tumor occurrence and development." (PMID 32546690, 2020). "These analyses encompass cell cycle genes (e.g., AURKA and CHEK1) that have been shown to be preferentially actionable against RB1 deficient tumor models." (PMID 32242058, 2020). "Being an important regulator of cell cycle progression and mitosis, AURKA has been described as an oncoprotein and a therapeutic target in various types of advanced tumours." (PMID 33078469, 2020). "AURKA inhibitors are also intensively studied in tumor therapy, but their effect on TME is less intensively investigated." (PMID 32472370, 2020). "For instance, MAP3K8 and AURKA identified by our phosphoproteomic interpretations are predictive biomarkers for treatment efficacy and mediators of anti-tumor activities in solid cancers." (PMID 32885042, 2020). "Specific inhibitors targeting AURKA has been developed and shown promising prospect recently due to the prominent role of AURKA in tumor progression." (PMID 33117697, 2020). "In the past several decades, emerging studies have proved that AURKA plays an important role in tumor development and progression." (PMID 33117697, 2020). "MLN8054 and MLN8237 disrupt stabilization of N-Myc by AURKA, by inducing conformational shifts away from the kinase active state, leading to N-Myc degradation, and suppression of tumor growth." (PMID 33167327, 2020). "Concerning the kinase family, AURKA overexpression promoted migration and invasion of oesophageal cancer cell lines and increased tumour size in vivo." (PMID 32429269, 2020). "The effect of AURKA-targeted inhibition of tumor growth plays roles in both the inactivation of AURKA activity and the decrease in the AURKA protein expression level." (PMID 31920463, 2020). "Aurora kinase A (AURKA) is a negative regulator of G2-M transition and is crucial in MYC amplified SCLC (around 20% of SCLC tumors): the inhibition of AURKA induces cell cycle arrest and strongly suppresses tumor growth in SCLC models." (PMID 31383005, 2019). "We have expected a synergistic effect of alisertib and FRAX1036 on cell cycle and suppression of tumor growth because of more effective suppression of AURKA in the settings of PAK1 inhibition." (PMID 31254157, 2019). "Materials and Methods: We assessed the expression profile of AURKA in 60 fresh GC and adjacent non-tumor tissues and 50 normal gastric specimen by qRT-PCR, and investigated the association of AURKA expression with clinicopathological features." (PMID 31871591, 2019). "We investigated the level of AURKA mRNA and miR-4715-3p expression in de-identified normal and tumor tissues." (PMID 31740746, 2019). "The AURKA inhibitor, Alisertib disrupts the interaction between N-MYC and AURKA and suppresses tumor growth significantly." (PMID 31547070, 2019).
tumor (continued). "The results showed significantly higher values of AURKA expression in GC tissues compared to adjacent non-tumor tissues and normal tissues (median of fold change expression, 42.58 vs 14.94, P< 0.001; 42.58 vs 9.49, p< 0.001 respectively)." (PMID 31871591, 2019). "This analysis was based on comparing tumor tissues which showed increased AURKA expression with normal gastric tissues." (PMID 31871591, 2019). "The fact that reduced expression levels of a mitotic gene lead to tumor appearance is a common issue for many other mitotic regulators such as AurKA, AurKB, PTTG1, and Mad2." (PMID 30862113, 2019). "MLN8237 (also known as alisertib), a second-generation orally bioavailable inhibitor of AURKA, is being investigated for treating advanced malignancies due to both its in vitro and in vivo activities against a broad range of tumor types." (PMID 31647033, 2019). "Enhanced anti-tumor activity of this combination is based on multiple mechanisms, including enhanced inhibition of phosphorylation of AURKA, PAK1, and ERα, as well as decreased expression of cell cycle proteins and C-MYC." (PMID 31254157, 2019). "Previous studies have found that AURKA was overexpressed in several common human malignancies, which in turn promoted cell proliferation and tumor progression and metastasis." (PMID 31636670, 2019). "Out of 330 microsatellite stable tumour samples, 217 (65.76%) had AURKA copy number aberration, determined by a segment mean threshold of 0.4 in the somatic copy number aberration data." (PMID 29760449, 2018). "Phosphorylation of AURKA (at T288) was evaluated in tumors from xenografts that did indeed progress to fulminant tumors (>200 mm3, tumor positive) in bexarotene- and vehicle-treated animals." (PMID 30518623, 2018). "Both AURKA and AURKB are implicated in tumour resistance pathways for selective EGFR inhibitors in cancer." (PMID 29115879, 2018). "Perhaps a mechanism to provide a greater anti-tumor effect than targeting AURKA alone is targeting both AURKA and AURKB through the use of pan-aurora inhibitors." (PMID 30326621, 2018). "We identified that AURKA is highly expressed in the leader cells during tumor collective invasion, which is responsible for the local invasion of malignant cells." (PMID 28592839, 2017). "We further clarified the role of AURKA polymorphisms in the clinicopathologic status of OSCC, such as the tumor clinical stage, tumor size, lymph node metastasis, and cell differentiation." (PMID 28152093, 2017). "Chromatin immunoprecipitation and NNMT promoter luciferase assays revealed that AURKA’s effects on NNMT were caused by PAX3-mediated transcriptional repression and overexpression of NNMT blocked tumor cell invasion in vitro." (PMID 28102366, 2017). "AURKA knockdown reduced tumour incidence, indicating that AURKA has an essential function in tumour initiation." (PMID 28114286, 2017). "The percentage of cells with 3–4 copies and as well as percentage of cells with more than 4 copies of AURKA were similar in tumor and urine samples from the same patient." (PMID 28102366, 2017). "Together, our study illustrates that AURKA acts as a potential therapeutic target for suppressing the process of tumor collective invasion." (PMID 28592839, 2017). "Recently, conformation-changing AURKA inhibitors, with one of them currently being tested in early clinical trials, have been reported to suppress tumor growth and prolong survival in mice bearing xenograft tumors of human HCC cells." (PMID 28903390, 2017). "miR-199a-3p functions as a tumor suppressor and inhibits tumor metastasis by repressing various oncogenes, such as mTOR,aurora kinase A, and c-MET.Previous analysis have indicated that miR-199a-3p expression is inhibited in various cancer types." (PMID 28743276, 2017). "The AURKA staining was positively correlated with tumor stage (P=0.006), clinical stage (P=0.002), lymph node metastasis (P=0.007) and distant metastasis (P<0.0001)." (PMID 28218735, 2017).